CD4 (CD4 molecule)
Diseases named in the same sentence as CD4 in open-access papers (continued):
Sharing a sentence is not in itself a finding about the gene and the disease.
leukocytosis (24 papers, 2012 to 2025). "Studies have linked DD to leukocytosis, an increased neutrophil-to-lymphocyte ratio, and an elevated CD4 + to CD8 + T-cell ratio." (PMID 40370665, 2025). "The absolute CD4 decrease was likely related to mycobacterial bone marrow invasion and subsequent inflammation causing pancytopenia and total leukocytosis." (PMID 24358876, 2013). "The authors hypothesized that the present CD4+ T cells were able to lower the bacterial load in the milk of infected udder quarters, e.g., through leukocytosis caused by their production of IL-17A and INF-γ." (PMID 35681803, 2022). "Substantial interindividual variability exists in CD4+ T cell measurements, with absolute counts being particularly susceptible to confounding factors including active infections, pharmacologic interventions, chronic inflammatory conditions, leukocytosis, and post-splenectomy status." (PMID 40895621, 2025). "In CARD11(E626K)CD4-Cre mice, leukocytosis and an increased number of CD4+ cells were observed in peripheral blood." (PMID 36446869, 2022). "Further assessment of the immune cell compartment during this treatment showed decreasing leukocytosis and granulocytosis, and the CD4/CD8 T cell ratio disclosed a relative increase in CD4+ T cells and decrease in CD8+ T cells." (PMID 35692034, 2022). "We found that the production of IL-17A and IFN-γ by circulating CD4+ lymphocytes of immunized cows correlated with the intensity of milk leukocytosis." (PMID 26375594, 2015). "Underlying the immediate leukocytosis were significant elevations in monocyte, neutrophil, IG, and lymphocyte counts, with the lymphocytosis driven by a significant increase in the absolute number of B cells, NK cells, NKT cells, and both CD4+ and CD8+ T cells." (PMID 28719602, 2017). "Leukocytosis, if present, is due to an increase in lymphocytes but the percentage of the different lymphocyte subpopulations (CD3, CD4, CD8, CD16, CD19) remains unchanged despite immune dysregulation." (PMID 23060872, 2012). "Our findings show that hot water immersion (38°C) likely attenuated the exercise-induced leukocytosis, and that the exercise-response of recently activated CD4 T cells and non-classical monocytes were modified according to the water temperature." (PMID 36051913, 2022). "Postoperative leukocytosis was observed in both groups as expected, while the number of CD4+ T cells were not significantly changed during 24-h perioperative period (the center panel)." (PMID 32854613, 2020). "Circulating leukocytosis after ALI was not reduced by colchicine therapy, but neutrophils reactivity and CD4 and CD8 cell surface expression on lymphocyte populations were restored." (PMID 33264297, 2020).
lipodystrophy (24 papers, 2006 to 2025). A congenital or acquired disorder characterized by abnormal loss or redistribution of the adipose tissue in the body. "Based on the results of our study, increasing age, nadir CD4 cell count > 350 cells/mm3, and presence of lipodystrophy increased the risk of developing hypertriglyceridemia." (PMID 28293638, 2017). "However, after adjustment for CD4 count (cells/mm3) and current cART, only D4T exposure was significantly associated with lipodystrophy." (PMID 38070936, 2023). "For multiple linear regression, variables age, sexual maturation, use of ART, CD4 lymphocytes, viral load, lipodystrophy (lipoatrophy), subscapular skinfold, calf skinfold and self-esteem remained in the model." (PMID 36361076, 2022). "Among the HIV covariates increasing CD4 category (p-trend=0.001) and lipodystrophy (p<0.001) were also independently predictive of new onset DM." (PMID 23078769, 2012). "Among HIV-related factors, recent CD4 counts of<200 cells/μL and lipodystrophy were predictive of new onset DM." (PMID 23078769, 2012). "In multivariate analysis, factors associated with hypertriglyceridemia were increased age (OR: 1.28, 95% CI: 1.02–1.61; p = 0.032), nadir CD4 cell count > 350 cells/mm3 (OR: 7.56, 95% CI: 1.68–34.03; p = 0.008), and presence of lipodystrophy (OR: 3.48, 95% CI: 1.01–12.01; p = 0.048)." (PMID 28293638, 2017). "Furthermore, patients with lipodystrophy had a higher systolic blood pressure and leukocyte count and a mean CD4+ cell count." (PMID 24958511, 2014). "In multivariate regression analysis, the relationship between healthcare utilization (encounters) and lipodystrophy status (represented as lipodystrophy assessment score) remained significant controlling for age, sex, HIV viral load, CD4 count, and presence of cardiovascular risk or HCV disease." (PMID 18593479, 2008). "Treatment interruption (TI) in patients with high CD4 cell counts, lipodystrophy, and limited options may be an alternative in resource-limited settings." (PMID 18031583, 2007). "PLWH with lipodystrophy were given 2 g/day of ALCAR for 48 weeks and showed an increase in mitochondrial DNA in circulating CD4+ T cells, implying an improvement in innate immunity and mitochondrial function." (PMID 34239993, 2021). "We identified a very high support for age (PEP: 84.5%), moderate for BMI (PEP: 49.3%), CD4/8 ratio (PEP: 44.2%) and lipodystrophy (PEP: 44.0%)." (PMID 28097068, 2017). "BMA provided a very high support for age (Posterior Effect Probability-PEP: 84.5%), moderate for BMI (PEP: 49.3%), CD4/8 ratio (PEP: 44.2%) and lipodystrophy (PEP: 44.0%)." (PMID 28097068, 2017). "Higher CD4 cell count, lower plasma HIV-1 RNA levels, clinical signs of lipodystrophy, longer exposure times to NNRTI and PI, and older age were all also associated with elevated cholesterol levels." (PMID 18923695, 2008). "CD4 cell count, HIV-1 RNA, lipid profile, and lipodystrophy were assessed at baseline and every 3 months." (PMID 18031583, 2007). "However, TI is not a good solution for lipodystrophy because TI of NNRTI-based regimens has a rapid CD4 decline and a high probability of early ART resumption." (PMID 18031583, 2007). "CD4 counts were higher (although not statistically significant) and the interquartile range of HIV viral loads was lower in subjects with lipodystrophy vs. subjects without lipodystrophy." (PMID 18593479, 2008). "Among HIV-infected women, median CD4 count was higher (p = 0.02) and median HIV viral load (p = 0.003) was lower in women with self-reported lipodystrophy, as compared to HIV-positive women without lipodystrophy." (PMID 16824226, 2006).
lung squamous cell carcinoma (24 papers, 2014 to 2025). "CD28 expression on CD39+ CD4+ T cells was positively correlated to lung squamous cell carcinoma (LUSC) risk (OR, 1.0335 [95% CI, 1.009–1.0586]), inversely mediated by IL-16 (95% CI, −0.01 to −0.0003)." (PMID 41292522, 2025). "For example, female patients with lung squamous cell carcinoma had significantly higher abundance of activated CD4 + T cells and activated CD8 + T cells." (PMID 36964522, 2023). "Specifically, the high m5C modification levels are positively correlated with neutrophils, resting CD4+ memory T-cells, and M2 macrophages in lung squamous cell carcinoma, and negatively correlated with follicular helper T-cells, CD8+ T-cells, and activated NK cells." (PMID 40279954, 2025). "LUAD showed significantly higher infiltrating levels of CD4+ T cells in TS, while lung squamous cell carcinoma (LUSC) was characterised by higher infiltrating levels of PD‐L1+ cells, CD133+ CSCs and macrophages both in TS and TN, suggesting immune suppressive milieu." (PMID 36588094, 2023). "Furthermore, Wang and Guo found decreased infiltration of resting memory CD4 T cells and increased infiltration of follicular helper T cells in patients with lung squamous cell cancer who smoked or had quit smoking for less than 15 years." (PMID 35529255, 2022). "Therefore, we assumed that TTN mutation might positively regulate macrophages M1, CD4, and CD8 T cells in lung squamous cell carcinoma." (PMID 34746153, 2021). "Additionally, FH expression was associated with immune infiltration, including B cells, CD4+ T cells, CD8+ T cells, neutrophils, macrophages, and dendritic cells, especially in liver hepatocellular carcinoma (LIHC), LUAD, and lung squamous cell carcinoma (LUSC)." (PMID 34737838, 2021). "In contrast, female displayed higher activity of CD4 + and CD8 + cells than in males with lung squamous cell cancer." (PMID 38212543, 2024). "Notably, PKM2 exhibited a strong correlation with B cells and CD4+ T cells in LUAD; and with B cells, CD8+ T cells, CD4+ cells, and macrophages in lung squamous cell carcinoma (LUSC)." (PMID 38097666, 2023). "Surprisingly, the results showed that whether in LUAD or lung squamous cell carcinoma (LUSC), moesin promotes the infiltration for a variety of immune cells including CD4+ T cells, CD8+ T cells, and DC cells." (PMID 33838692, 2021). "There were contradictory results between liver hepatocellular carcinoma and lung squamous cell carcinoma in the correlations of PINK1 expression with immune infiltration, including infiltration of B cells, CD8+ T cells, CD4+ T cells, macrophages, neutrophils, and dendritic cells." (PMID 33244455, 2020). "Then, to eliminate the effect of lung squamous cell carcinoma we used another scRNA-seq dataset from GSE131907 to unravel the expression level in LUAD, indicating that it was relatively higher expressed at CD8 Tex(0.11), CD8 T cells(0.08), B cells(0.08) and CD4 T cells(0.07) over other cells(≤0.05)." (PMID 35090416, 2022).
Miscarriage (24 papers, 2012 to 2026). A pregnancy that ends at a stage in which the fetus is incapable of surviving on its own, defined as the spontaneous loss of a fetus before the 22th week of pregnancy. "We found that among HIV-infected women, miscarriage was associated with CD4 cell counts <350 cells/mm3." (PMID 22937874, 2012). "In multivariable analysis, only CD4 cell counts <350 cells/mm3 was significantly associated with miscarriage." (PMID 22937874, 2012). "CD4 cell counts <350 cells/mm3 and history of miscarriage were associated with an increased risk of miscarriage." (PMID 22937874, 2012). "In addition, the abnormality in number and functionality of dCTLA-4+Tim-3+CD4+T cells was associated with miscarriage." (PMID 30622243, 2019). "The levels of CD4 T cells have been noted to be decreased in the decidua and peripheral blood of women with miscarriages compared with fertile controls." (PMID 36968684, 2023). "The abnormality in number and functionality of dCTLA-4+Tim-3+CD4+T cells is at least one of the reasons leading to the occurrence of miscarriage." (PMID 30622243, 2019). "In the present study, efficacy studies of anti-CTLA-4 and anti-Tim-3 were first done in mouse pregnancy models, and then the expression and function of CTLA-4/Tim-3 on CD4+T cells during normal pregnancy and miscarriage were explored." (PMID 30622243, 2019). "Women who have experienced miscarriage have reduced numbers of Treg cells, including CD4+ cells, in their blood compared with women who experience healthy pregnancies." (PMID 31842980, 2019). "The reduction of the population of circulating CD4+CD25+Foxp3+ regulatory T cells exhibit impaired immune regulatory mechanisms in pregnancy complicated by miscarriage." (PMID 25945787, 2015). "In our findings the percentage of circulating CD4+CD25+Foxp3+ T cells was significantly lower in miscarriage in comparison to normal pregnancies (p = 0.003)." (PMID 25945787, 2015). "Thus, CD8+ memory differentiation appears more dynamically reshaped after miscarriage than CD4+ helper subsets." (PMID 41301892, 2025). "Th1 and Th17 cells, known to be responsible for acute allograft rejection, could be involved in miscarriage and Th2 cells together with regulatory CD4+ T cells, known to be involved in allograft tolerance, could be responsible, at least in part, for the success of pregnancy." (PMID 26064081, 2015). "Furthermore, the expression of CTLA-4 on the surface of CD4+CD25high cells, a molecule responsible for inhibition of T cell proliferation and transmission of the inhibitory signals, was increased in normal early pregnancy, and reduced in miscarriage." (PMID 25945787, 2015). "Previous studies reported that CD4+, CD25+, and Treg cells were downregulated in peripheral lymphocytes and metaphase lymphocytes of women who had a miscarriage." (PMID 37035756, 2023). "It has been shown that recurrent miscarriage patients produce more CD4+IL17+ and CD4+IFNG+ cells and fewer CD4+CD25+FOXP3+ Tregs, compared to fertile controls, when CD4+ T cells are cultured with DCs and partner's seminal fluid antigens." (PMID 30984163, 2019). "In our sample, the CD4/CD8 ratio was statistically significantly positively correlated with the (%) NK cell proportion in the total population and among women with IVF-ET failures and with the (%) HLA-DQA1 sharing in the group with miscarriages." (PMID 36968684, 2023). "During a normal pregnancy, there is an increase in the number of Treg cells CD39+ CD4+ % CD4+, while studies suggest that a decrease in these cells among PCOS patients could contribute to miscarriage or infertility." (PMID 38189053, 2023). "Furthermore, although newborns naturally tend to exhibit a Th-2 skewed immune response to reduce miscarriage, IL-12, INF-γ, and CD3+/CD4+/Tbet increases observed in CSD pups point out a pro-inflammatory Th-1 response linked to CSD." (PMID 37394428, 2023).
Miscarriage (continued). "The CD4/CD8 ratio showed positive correlations with the (%) NK cell proportion among women with IVF-ET failures and with the (%) HLA-DQA1 sharing in the group with miscarriages, which translates into a trend of co-existence of immunological risk factors in this population." (PMID 36968684, 2023). "Prior investigations did not make comparative measurements of IL-17 production by decidual CD4+ T cells in normal pregnancy and miscarriages and none identified Th17 subpopulations able to produce IL-4 or IFN-γ together with IL-17 (Th17/Th2 and Th17/Th1, respectively)." (PMID 26798325, 2016).
pancreatic ductal adenocarcinoma (24 papers, 2018 to 2025). An infiltrating adenocarcinoma that arises from the epithelial cells of the pancreas. "Napsin B Aspartic Peptidase, Pseudogene (NAPSB) was associated with CD4 + T cell infiltration in pancreatic ductal adenocarcinoma." (PMID 35987606, 2022). "Napsin B Aspartic Peptidase, Pseudogene (NAPSB) is a pseudogene that has been identified to be associated with the infiltration of CD4 + T immune cells in pancreatic ductal adenocarcinoma (PDAC)." (PMID 35987606, 2022). "High CD8+ and Th1-polarized CD4+ T cell infiltration is associated with prolonged survival in human pancreatic ductal adenocarcinoma (PDAC)." (PMID 33803936, 2021). "Pancreatic ductal adenocarcinoma is also associated with an increase in peripheral Th cells, characterized as CXCR5−PD1hi CD4+ T cells, which have been associated with the activation of B cells in inflamed tissues." (PMID 38686549, 2024). "We thus tested the plasma of patients with pancreatic ductal adenocarcinoma (PDAC) for the presence of inhibitory PLA2G1B activity that impairs the CD4 T-cell response to IL-7." (PMID 35392090, 2022). "In this work, we analyze the expression levels and prognostic value of stromal tumor-infiltrating lymphocyte (CD4, CD8, and CD20) and cancer-associated fibroblast (Thy-1, FAP, and SMA) subpopulations in a cohort of pancreatic ductal adenocarcinoma patients." (PMID 34771664, 2021). "In addition, anti- PD-1 immunotherapy manipulated CD4+ T cell chemotaxis response by reshaping CD11b+ neutrophil degranulation activity, which was considered a clinical indicator of successful pancreatic ductal adenocarcinoma (PDAC) immunotherapy." (PMID 37889543, 2023). "Notably, the bacteria Porphyromonas gingivalis, which is associated with pancreatic ductal adenocarcinoma (PDAC), encodes such a cofactor protein and increased PLA2G1B activity in PDAC patient plasma inhibits the CD4 response to IL-7." (PMID 35392090, 2022). "Previously, we found that CMAS KO in a murine model resulted in enhanced infiltration of CD4+ and CD8+ T cells within the tumor microenvironment of pancreatic ductal carcinoma and improved survival outcomes." (PMID 40718829, 2025). "Mirlekar and Pylayeva-Gupta found that IL35 is an important immunosuppressive driver in pancreatic ductal adenocarcinoma (PDA) and potentiates tumor growth via the suppression of endogenous antitumor CD4+ effector T cell responses." (PMID 39291183, 2022). "In surgically resected pancreatic ductal adenocarcinoma (PDAC) patients, higher tumour infiltrating CD4+ and CD8+ cells can correlate with better survival." (PMID 34680355, 2021). "In pancreatic ductal adenocarcinoma, CXCL10 has been shown to recruit CD4+, CD8+, and CXCR3+ T cells as well as FOXP3+ Tregs27." (PMID 34504204, 2021). "Immunohistochemistry was used to explore the clinical significance of CD3, CD4, CD8, FoxP3, and PD-L1 expression within the TME and to identify correlations with the prognosis of PC in a series of 29 patients with ASCP and 54 patients with pancreatic ductal adenocarcinoma (PDAC)." (PMID 36835933, 2023).
Pancytopenia (24 papers, 2013 to 2026). An abnormal reduction in numbers of all blood cell types (red blood cells, white blood cells, and platelets). "In CD4+ T cell count >50/microliter, all typical clinical symptoms of VL including hepatosplenomegaly, weight loss, and pancytopenia can be seen but in CD4+ T cell count <50/μL the disease appears with atypical clinical manifestations." (PMID 26075117, 2015). "Laboratory studies demonstrated severe immunosuppression with a CD4 count of 4 cells/μL and pancytopenia." (PMID 41328101, 2025). "Most patients (96 [78%]), had a positive HIV test result, pancytopenia, and were severely immunosuppressed; however, only 40 (42%) patients had baseline CD4 counts of ≤50 cells/mL3." (PMID 39682590, 2024). "With the presence of pancytopenia and a CD4 count of 33, the patient responded well to treatment and recovered." (PMID 39104429, 2024). "With a low CD4 count of 33 and symptomatic pancytopenia, a chemotherapy regimen comprising rituximab and doxorubicin was administered." (PMID 39104429, 2024). "The combination of Pancytopenia plus < 50 CD4 + cells/μL showed a sensitivity of 84%, but a low specificity (57%)." (PMID 34384448, 2021). "A 45-year-old HIV-infected male patient with a CD4+ T lymphocyte count of 26 cells/μL who presented to the emergency department with fever and pancytopenia." (PMID 30832607, 2019). "Laboratory findings revealed pancytopenia and CD4+ levels of 622 cells/μL with an undetectable viral load." (PMID 29155831, 2017). "Patients with pancytopenia were more likely to be unemployed (87.5% vs. 72.5%), to have lower BMI (mean (SD): 22.0 (4.0) vs. 25.1 (5.3)) and have a lower CD4 cell count (0–100 cells/μL: 68.4% vs. 23.1%)." (PMID 26703689, 2015). "Cyclosporine reduces CD4+ and CD8+ T cells in the epidermis, methotrexate inhibits DNA synthesis in immunologically active cells and causes pancytopenia, and azathioprine suppresses T-cell function, B-cell antibody production, and ability of Langerhans cells to present antigens." (PMID 32138191, 2020). "Admission labs showed severe pancytopenia (Hb 6.2 g/dL, WBC 1,590/μL, platelets 102,000/μL) and a CD4 count of 164 cells/mm3." (PMID 41695016, 2026). "Consequently, adoptive multi-transfusion of mMDSCs reduced the intra-BM frequencies of CD4+ and CD8+ T lymphocyte, decreased intra-BM IFN-γ concentration, and ameliorated pancytopenia as well as BM destruction of AA mice." (PMID 35851002, 2022). "The CD4 count was not performed in 27 HIV-positive patients with pancytopenia, thus the proportion of patients with advanced HIV may be underestimated." (PMID 35747558, 2022). "In individuals with human immunodeficiency virus (HIV) infection, the prevalence of pancytopenia has been reported to be approximately 8.7%, with affected patients exhibiting lower body mass index, reduced CD4 counts, and higher HIV viral loads compared to those without pancytopenia." (PMID 40901202, 2025).